PEA15 (proliferation and apoptosis adaptor protein 15)
Diseases named in the same sentence as PEA15 in open-access papers (continued):
Sharing a sentence is not in itself a finding about the gene and the disease.
glioma (6 papers, 2003 to 2022). A benign or malignant brain and spinal cord tumor that arises from glial cells (astrocytes, oligodendrocytes, ependymal cells). "PEA15 is a caspase-8 inhibitor and is upregulated in various glioma cell lines and correlates with the resistance of human glioma cells to anticancer drugs, such as TRAIL." (PMID 35328780, 2022). "Phosphorylation of PEA-15 at Ser116 is highly abundant in astrocytomas and glioblastomas, which renders glioma cells resistant to glucose deprivation-mediated cell death." (PMID 26263999, 2015). "PEA-15 modulates coxsackievirus–adenovirus Receptor (CAR) expression and adenoviral infectivity via ERK-mediated signals in glioma cells, representing PEA-15 as a predictive marker in glioblastoma." (PMID 26263999, 2015). "It has also been reported that PED/PEA-15 protein inhibits TRAIL-induced apoptosis of glioma cells, and cell lines overexpressing the erbB-2 receptor are resistant to TRAIL-mediated apoptosis." (PMID 12610517, 2003). "PEA-15 also regulates JNK (c-Jun N-terminal Kinase) signaling to promote autophagy in glioma cells." (PMID 26263999, 2015). "Similarly, glioma cell lines resistant to TRAIL were found to have a two-fold increase in PEA-15 expression and inhibition of PKC re-established sensitivity to TRAIL, implicating phosphorylation of PEA-15 in this process." (PMID 24657708, 2014). "This flavonoid induced rapid apoptosis in glioma cells resistant to TRAIL, in addition to the downregulation of phosphoprotein enriched in astrocytes 15 (PEA15), as key regulators of cell death." (PMID 35057010, 2022). "Major discriminator between high-grade and low-grade tumors included CRYAB, IPYR, TPIS, PEA15, PSD13, GFAP, IDH3A, 6PGL, PHP14, KCRB as overexpressed in low-grade gliomas; HCD2, HBA, HBD as overexpressed in high-grade GBM." (PMID 25050814, 2014). "HBA, HBD and HCD2 positively correlated with high-grade gliomas; GFAP, PHP14, 6PGL, PSD13, PEA15, TPIS, CRYAB_b, IPYR and IDH3A correlated with low-grade tumors; on the other hand, NFM, CN37, NDUS1 and MDHC negatively correlated with tumor samples." (PMID 25050814, 2014). "The phosphorylation of PEA-15 is required for activation of JNK and inducing glioma cell autophagy." (PMID 26263999, 2015). "Twelve major discriminators between low- and high-grade gliomas were identified: HCD2, HBA and HBD were up-regulated in high-grade gliomas, whereas expression levels of CRYAB_b, IPYR, TPIS, PEA15, PSD13, GFAP, IDH3A, 6PGL and PHP14 were found to be higher in low-grade than in high-grade tumors." (PMID 25050814, 2014).
glioblastoma (5 papers, 2014 to 2020). The most malignant astrocytic tumor (WHO grade IV). "PEA-15 phosphorylation at Ser116 rendered glioblastoma cells resistant to glucose-deprivation mediated cell death, which is in line with our finding that unphosphorylatable PEA-15 can potentiate cytotoxic effects." (PMID 32102425, 2020). "Upregulation of PEA-15 also led to an increase in resistance to glucose deprivation-induced apoptosis of glioblastoma cells and an increase in phosphorylation at Ser116 of PEA-15 was evident in perinecrotic areas." (PMID 24657708, 2014). "Further, PEA15 phosphorylation at Ser116 was shown to be required for blocking apoptosis in glucose-deprived glioblastoma cells." (PMID 25096718, 2014). "However, DR5-mediated DISC was modified by several anti-apoptotic proteins including PEA-15 resulting in TRAIL resistance in glioblastoma." (PMID 24657708, 2014). "PEA-15 was found to interact with 67LR in both PED/PEA-15-transfected HEK-293 cells and in U-373 glioblastoma cells." (PMID 26263999, 2015). "PEA-15 is known to be upregulated in a variety of cancer subsets including immortal cancer cell lines (e.g. MCF-7 and HeLa cells), malignant pleural mesothelioma cells, breast cancer cells, non-small cell lung cancer (NSCLC) cells, glioblastoma and renal cell carcinomas." (PMID 24657708, 2014).
Insulin resistance (5 papers, 2013 to 2025). Increased resistance towards insulin, that is, diminished effectiveness of insulin in reducing blood glucose levels. "Some ATF2 target genes, for example, BDNF and PEA15, are also linked to the development of insulin resistance under glucose stimulation." (PMID 32993798, 2020). "Together, this suggests that an involvement of PEA-15 in PCOS as well as in the insulin resistance, commonly associated with the disease, and by targeting PEA-15 or a component of the signalling pathway by pharmacological intervention could potentially alleviate some of the symptoms of PCOS." (PMID 24657708, 2014).
hepatocellular carcinoma (4 papers, 2013 to 2026). A malignant tumor that arises from hepatocytes. "In the publication at hand, we focus on the characterization of the miR-449a-5p targetome and analyze the impact of miR-449a-5p and its target genes PEA15, PPP1CA and TUFT1 on the efficacy of sorafenib in hepatocellular carcinoma." (PMID 34976171, 2022). "To determine the relevance of PEA15, PPP1CA and TUFT1 in hepatocellular carcinoma in vivo, we analyzed three publically available expression datasets of primary HCCs." (PMID 34976171, 2022). "In this study, we comprehensively investigated the impact of miR-449a-5p and its target genes PEA15, PPP1CA and TUFT1 on the effects of sorafenib treatment in hepatocellular carcinoma." (PMID 34976171, 2022). "Our findings demonstrate that PEA15, PPP1CA and TUFT1 are frequently overexpressed in HCC and that patients with hepatocellular carcinoma may benefit from the repression of these genes." (PMID 34976171, 2022). "In the following, we focused on PEA15, PPP1CA and TUFT1 because they showed a strong regulation in qRT-PCR and literature research of these genes indicated promising approaches for the treatment of hepatocellular carcinoma." (PMID 34976171, 2022).
melanoma (4 papers, 2019 to 2023). A malignant, usually aggressive tumor composed of atypical, neoplastic melanocytes. "Targeting negative regulators of MAPK signaling inhibitors such as DUSP4 and PEA15 further activates MAPK signaling and may therefore be particularly effective in eliminating melanoma cells that have acquired resistance to BRAF and MEK inhibition." (PMID 32767816, 2021). "Deletion of negative ERK regulators, including DUSP4, DUSP6, and PEA15, induced cell death in BRAF and NRAS mutant melanomas due to unrestrained activation of ERK." (PMID 37803324, 2023).
triple-negative breast carcinoma (4 papers, 2014 to 2024). An invasive breast carcinoma which is negative for expression of estrogen receptor (ER), progesterone receptor (PR), and human epidermal growth factor receptor 2 (HER2). "Conversely, PGR, PDK1, and PEA15 are associated with Luminal A. Interestingly, in triple-negative breast cancer and ovarian cell lines, increasing PEA15 levels was shown to have an antitumor effect." (PMID 25183703, 2014). "PEA-15 can also promote ER-anchored protein tyrosine phosphatase PTP1B functions to dephosphorylate EGFR in triple negative breast cancer (TNBC) cells, down-regulating EGFR signaling in cancer cells." (PMID 26263999, 2015). "High ERK1/2 levels were found to correlate with PEA-15 expression and shorter survival times in patients with triple-negative breast cancer." (PMID 24657708, 2014). "In triple negative breast cancer, PEA15 functions in supporting metastasis and EMT." (PMID 39199676, 2024). "Moreover, PEA-15 blocked tumourigenesis in a triple-negative breast cancer xenograft model by an ERK1/2-dependent mechanism with overexpression of PEA-15 resulting in elevated caspase-8-dependent apoptosis." (PMID 24657708, 2014).
Alzheimer disease (3 papers, 2014 to 2024). A progressive, neurodegenerative disease characterized by loss of function and death of nerve cells in several areas of the brain leading to loss of cognitive function such as memory and language. "PEA15 was also found to be expressed in plaque-associated reactive astrocytes in post-mortem human Alzheimer’s disease (AD) tissue, so it was proposed as a biomarker of AD, along with other pathological hallmarks, to assess the severity of the disease progress at the time of death." (PMID 39201424, 2024). "PEA-15 was one of 20 proteins which was significantly reduced in the hippocampus and cerebral cortex of the Alzheimer's disease transgenic model." (PMID 24657708, 2014). "In these plaques, PEA-15 expression was increased compared to controls and confirmed in humans by studying amyloid plaques from post-mortem Alzheimer's disease brains." (PMID 24657708, 2014).
non-small cell lung carcinoma (3 papers, 2015 to 2020). A group of at least three distinct histological types of lung cancer, including non-small cell squamous cell carcinoma, adenocarcinoma, and large cell carcinoma. "For example, the expression of PEA15 was found to be increased in non-small cell lung cancer, chronic lymphocytic leukemia, thyroid cancer, prostate cancer and liver cancer cells, where it inhibited apoptosis and promoted tumor growth." (PMID 33246486, 2020). "PEA-15 was also identified to express strongly in various lung tumor types, and the high level expression of PEA-15 in non-small cell lung cancer (NSCLC) cell line is correlated with the resistance of TRAIL-induced cancer cell death." (PMID 26263999, 2015). "In non-small cell lung cancer, miR-212 increases TRAIL-mediated cell death by targeting anti-apoptotic protein PED/PEA-15 (phosphoprotein enriched in astrocytes 15) and targets synaptic acetylcholinesterase functioning as a tumor suppressor." (PMID 29190894, 2017).
Obesity (3 papers, 2011 to 2021). Accumulation of substantial excess body fat. "Indeed, recent work from our group has shown over-expression of Ped/pea-15 mRNA in the tibialis skeletal muscle of C57Bl/6 mice in which obesity is induced by high fat (HFD) feeding." (PMID 23585839, 2013).
B-cell chronic lymphocytic leukemia (2 papers, 2009 to 2020). "PEA-15 is a member of the death effector domain (DED) protein family known to control cell survival, and specific down-regulation of this protein sensitizes B-cell chronic lymphocytic leukemia cells to TRAIL-induced apoptosis." (PMID 19539371, 2009).
breast tumor (2 papers, 2023). "However, downregulated secretome markers FN1, PSMB6, PRDX4, and PEA15 are also upregulated at the mRNA level in breast tumors." (PMID 37128318, 2023). "Three downregulated markers, PEA15, PRDX4, and FN1, also showed low protein expression in breast tumors, as confirmed with immunohistochemistry staining." (PMID 37128318, 2023). "In breast tumor cells, PPP4C can act as either an anti-tumor factor promoting cell apoptosis through PEA15 regulation or an oncogenic factor facilitating proliferation and migration in a cell-content dependent manner." (PMID 37353511, 2023).
liver cancer (2 papers, 2020 to 2022). An epithelial or non-epithelial malignant neoplasm that arises from the liver. "In all three datasets the expression levels of PEA15, PPP1CA and TUFT1 were significantly increased in liver cancer tissue compared to adjacent non-tumorous liver tissue." (PMID 34976171, 2022).
lung carcinoma (2 papers, 2020 to 2021). "Similarly, other studies in cervical cancer and lung cancer reported that the unphosphorylated form of PEA15 serves as a tumor suppressor." (PMID 34241740, 2021). "Similarly, another study revealed the gain of PEA15 expression antagonized and its loss enhanced CCT68127-mediated growth inhibition in lung cancer." (PMID 32047549, 2020).
malignant glioma (2 papers, 2015 to 2022). A grade III or grade IV glioma arising from the central nervous system. "In human malignant glioma cell lines, PEA-15 mRNA is expressed two-fold higher levels in tumor necrosis factor-related apoptosis-inducing ligand (TRAIL)-resistant cell lines compared to sensitive cells, while c-FLIP mRNA expression is similar in both sensitive and resistant cells." (PMID 34997083, 2022). "PEA-15 was also reported to protect malignant glioma cells from TNF-related apoptosis-inducing ligand (TRAIL) mediated apoptosis, and TRAIL resistant effect depends on both PKC and CaMKII activities, suggesting doubly-phosphorylated PEA-15 is responsible for the anti-apoptotic effect of PEA-15." (PMID 26263999, 2015).
neuroblastoma (2 papers, 2014 to 2021). Neuroblastoma (NB) is the most common solid, extracranial childhood tumor. "PEA-15 was also one of the most highly phosphorylated proteins detected in neuroblastoma endosomes (fourth topmost phosphorylated protein in endosomes)." (PMID 34615962, 2021). "In addition to impairment of cell migration and proliferation, PEA-15 expression correlates with good prognosis in neuroblastoma and a 25% increase in patient survival time with the highest PEA-15 levels found in early stage tumours." (PMID 24657708, 2014).
ovarian tumor (2 papers, 2020 to 2021). "Our group demonstrated that stable expression of the unphosphorylated PEA15 led to significant inhibition of ovarian tumor growth in vivo even though phosphomimetic PEA15 also showed inhibitory effects in cell proliferation, colony formation and cell migration in 2D-culture system." (PMID 34241740, 2021).
Anxiety (1 paper, 2009). Intense feelings of nervousness, tension, or panic often arise in response to interpersonal stresses. "PEA-15 null mice also had deficient forepaw strength and in limited instances, heightened stress reactivity and/or anxiety." (PMID 19917132, 2009). "The PEA-15 null mice also exhibit reduced nocturnal activity and complex changes in behavior related to exploration of stress- or anxiety provoking environments." (PMID 19917132, 2009).
asthma (1 paper, 2020). "In addition to these four apoptosis-related genes (TRIO, PEA15, KLRK1, NDUFA13), we also found that the other genes in desensitization-treatment-related module exhibiting distinct degree of correlations to asthma via literature review." (PMID 32948203, 2020). "Notably, LINC02145 exhibited to be correlated to six asthma-related genes, including ZFN19, G2E3, ATF7IP, PEA15, SPDYE6, VWA5A." (PMID 32948203, 2020).
astrocytic tumor (1 paper, 2015). A glial tumor of the brain or spinal cord showing astrocytic differentiation. "PEA-15 expression levels were found to be inversely associated with malignancy grade of astrocytic tumors, and high PEA-15 expression was correlated to longer overall survival." (PMID 26263999, 2015).
atherosclerosis (1 paper, 2021). A disease characterized by the build-up of fatty material and calcium deposition in the arterial wall resulting in partial or complete occlusion of the arterial lumen. "To examine this, we used the well-established mouse model of atherosclerosis ApoE−/−, and crossed these to the PEA-15−/− mice to ApoE−/−/PEA-15−/− mice." (PMID 33772049, 2021). "Thus, we propose that lipid overflow from WAT is significantly reduced in PEA-15−/− mice, due to an enhanced adipocyte expansion capacity and that this prevents ectopic lipid accumulation in other tissues and protects against atherosclerosis." (PMID 33772049, 2021).
diabetic nephropathy (1 paper, 2012). "Transgenic mice overexpressing PEA15 have glomerular mesangial expansion and a histological pattern similar to diabetic nephropathy." (PMID 22813067, 2012).
endometrial cancer (1 paper, 2024). Primary or metastatic malignant neoplasm involving the endometrium (mucous membrane that lines the endometrial cavity). "The upregulation of PEA-15 (phospho-enriched protein in astrocytes), which exhibits both tumor-suppressor and -promoting properties, warrants further investigation to understand the relevance of this expression pattern in endometrial cancer." (PMID 39766121, 2024).
esophageal carcinoma (1 paper, 2020). A primary or metastatic malignant neoplasm involving the esophagus. "For instance, PEA15 protein was found to be highly in esophageal carcinoma and over expression of PEA-15 shortened the average survival time of patients." (PMID 32047549, 2020).
Huntington disease (1 paper, 2014). Huntington disease (HD) is a rare neurodegenerative disorder of the central nervous system characterized by unwanted choreatic movements, behavioral and psychiatric disturbances and dementia. "Differential expression of PEA-15 in the brain has also been associated with neurological disorders such as Alzheimer's and Huntington's diseases." (PMID 24657708, 2014). "Using mouse models for different neurodegenerative disorders (including Huntington's disease, the prion disease Scrapie and a model of impaired synaptic transmission), a proteomic study identified PEA-15 as a protein with decreased expression in all these disease models." (PMID 24657708, 2014).
latent infection (1 paper, 2013). "For instance, experimental latent infection of granulocyte–macrophage progenitors has been shown to result in long-term up-regulation of PEA-15 RNA." (PMID 24284875, 2013). "Furthermore, given that it has been shown that the UL138 gene product up-regulates TNFR1 expression during lytic and latent infection, potentially sensitising latently infected cells to TNFR1 mediated apoptosis, the concomitant up-regulation of PEA-15 would be a sensible pro-survival strategy." (PMID 24284875, 2013). "As PEA-15 is an anti-apoptotic factor that blocks both TNFR1 and Fas-L triggered apoptosis, clearly its up-regulation could be part of a protective response mediated by latent infection." (PMID 24284875, 2013).
Lissencephaly (1 paper, 2020). A spectrum of malformations of cortical development caused by insufficient neuronal migration that subsumes the terms agyria, pachygyria and subcortical band heterotopia. "In addition to identification of PEA15 as a candidate gene for human lissencephaly, our work provides a new opportunity to investigate developmental mechanisms that underlie unique aspects of neurodevelopment in gyrencephalic species." (PMID 33290415, 2020).
lymph node metastasis (1 paper, 2020). "Moreover, patients with high stage (III-IV vs I-II) (P = 0.001) and lymph node metastasis (P = 0.005) had higher expression of PEA15." (PMID 32047549, 2020). "High expression of PEA15 was strongly related with adverse clinicopathological parameters of EOC, including FIGO stage and lymph node metastasis." (PMID 32047549, 2020).
papilloma (1 paper, 2014). A benign epithelial neoplasm that projects above the surrounding epithelial surface and consists of villous or arborescent outgrowths of fibrovascular stroma. "Mice overexpressing PEA-15 also displayed an increase in skin tumourigenesis with a four-fold increase in papilloma number compared to their wild type littermates, suggesting a potential role for PEA-15 in tumour formation and cancer progression." (PMID 24657708, 2014).
periodontitis (1 paper, 2024). An acute or chronic inflammatory process that affects the tissues that surround and support the teeth. "MR analysis corroborated the inferences drawn from scRNA-seq, identifying ten causal gene markers associated with periodontitis, including LIMA1, PEA15, TMEM158, CMTM6, PDP1, FFAR4, VAC14, and ENHO." (PMID 39830509, 2024).
sarcopenia (1 paper, 2022). Progressive decline in muscle mass due to aging which results in decreased functional capacity of muscles. "The top three identified hub genes are UPF3A, CSTB and PEA15, which were all affiliated to common genes of sarcopenia and proliferating myoblasts of T2DM." (PMID 35271662, 2022).
serous ovarian cancer (1 paper, 2020). "For this purpose, correlation of PEA-15 phosphorylation with therapy outcome in high-grade serous ovarian cancer is needed, as this subtype is the most aggressive and has the worst prognosis." (PMID 32102425, 2020).
skin cancer (1 paper, 2020). "Several studies have shown that PEA15 has a pro-survival and tumorigenic PEA15 in skin cancer." (PMID 32047549, 2020).